CXCR4 (C-X-C motif chemokine receptor 4)
Diseases named in the same sentence as CXCR4 in open-access papers (continued):
Sharing a sentence is not in itself a finding about the gene and the disease.
tumor (continued). "The CXCL12/CXCR4 axis, together with a variety of other factors, regulated tumor growth and metastasis in OC and the concomitant expression of CD40 and CXCR4 in OC was strongly associated with pelvic metastasis." (PMID 36642706, 2023). "In contrast, however, the over-proportional increase in tracer accumulation in the OCI-LY1 xenograft is in line with our in vitro findings, i.e., a dexamethasone-treatment induced CXCR4 upregulation on the tumor cells." (PMID 37162652, 2023). "CXCR4 is highly expressed on tumor cells and can promote tumor cell growth, migration, and invasion." (PMID 37626511, 2023). "SDF-1α can regulate tumor cell proliferation, motility, epithelial–mesenchymal transition and metastasis by binding to CXCR4 and activating downstream signaling." (PMID 37929799, 2023). "In this study, we reflect on the importance of focusing on the CXCR4 expression analysis in the stroma of PDAC-diagnosed patients, due to the high expression of CXCR4 in the tumor stroma." (PMID 37697316, 2023). "In the n1 cohort, cytoplasmic CXCR4 expression was observed in 98% of benign kidney tissue samples, whereas only 38.9% of the ccRCC tumor tissue samples showed an expression of CXCR4." (PMID 36982302, 2023). "The variables taken into consideration are BRAF, KRAS, NRAS mutations, the expression of fibronectin, CXCR4, and FAP in terms of intensity in both the primary tumor and metastases, and the number of metastases." (PMID 37892020, 2023). "The in vivo profile was analyzed in u87.CXCR4 tumor xenografted mice using μPET/CT and an ex vivo biodistribution study at 75 min." (PMID 37318633, 2023). "CTLs engineered to overexpress the chemokine receptor CXCR4 displayed increased homing to the bone marrow and engraftment, and acquired greater anti-tumor immunity." (PMID 37261345, 2023). "The CXCL12/CXCR4 axis plays a crucial role in tumor–stromal cell interactions, leading to progression-related behaviors such as angiogenesis, migration, and metastasis." (PMID 37444525, 2023). "Enhanced expression of stromal cell-derived factor 1 (SDF1) and C-X-C motif chemokine receptor 4 (CXCR4) in the tumor microenvironment can promote tumor proliferation and migration." (PMID 37509689, 2023). "We found that tumor cells primarily affected immune cell types via MIF-(CD74 + CXCR4) ligand-receptor pairs." (PMID 38123589, 2023). "XIST+ tumor cells were most abundant in the IgG group, in which regulation of cell adhesion, the CXCR4 pathway, and ALK signaling in cancer were enriched." (PMID 37430270, 2023). "To investigate the link between CXCR4 and tumor-infiltrating B lymphocytes in GC, we performed immunohistochemical analysis with a GC tissue chip containing 80 pairs of clinical samples." (PMID 37629071, 2023). "The CXCL12/CXCR4 axis activates multiple pathways involved in angiogenesis, metastasis, and survival in the tumor microenvironment and promotes tumor cell invasion and metastasis." (PMID 37311820, 2023). "CAFs secreted CXCL12/SDF-1, which contributes to tumor growth and anti-apoptosis in cancer cells via CXCR4." (PMID 37005661, 2023). "Here, the authors indicate that eliminating CXCL12 expression on afferent lymphatics or blocking CXCR4 on T cells led to retention of T cells at the tumor site and better tumor control." (PMID 37662908, 2023). "Overall, 81 tumours (77.1%) showed immunohistochemical CXCR4 protein expression with 30 (28.6%) with Score 1; 24 (22.9%) with Score 2; and 27 (25.7%) with Score 3, respectively." (PMID 37047331, 2023). "Overall, 77.1% of the analysed tumours showed CXCR4 protein expression (25.7% of them at high expression level (Score 3))." (PMID 37047331, 2023).
tumor (continued). "CXCR7 mediates the internalization of effective ligands and the degradation of chemokine secretion while regulating the expression of CXCR4 in tumor development." (PMID 37626511, 2023). "CXCR4 is overexpressed in numerous human cancers including glioma, and it has been shown to promote tumor growth, invasion, angiogenesis, metastasis, relapse, and therapeutic resistance." (PMID 37190507, 2023). "C-X-C chemokine receptor 4 (CXCR4) is widely overexpressed in various types of cancer and is involved in several cancer phenotypes including tumor growth, survival, and metastasis." (PMID 36732336, 2023). "The C-X-C chemokine receptor 4 (CXCR4) is highly expressed in more than 23 kinds of human tumor cells and is a prognostic marker." (PMID 36762192, 2023). "To study the efficacy of CXCR4 inhibition and local single-dose RT on primary PCa tumor growth, we used an orthotopic PCa xenograft model–human C4-2B in immune-deficient nude mice." (PMID 36831366, 2023). "Future studies should reveal the impact of these differential effects of CXCR4 inhibition on stroma versus cancer cells, in different microenvironmental conditions, on tumor progression, vascular structure, and function." (PMID 36831366, 2023). "Of course, silencing the expression of CXCR4 can also inhibit some targets that induce tumor cell migration activity." (PMID 37691919, 2023). "For example, conjugate tumor-targeted cytotoxic nanoparticles have been explored by targeting the chemokine receptor 4 (CXCR4), which is overexpressed in more than 23 human cancers." (PMID 37895165, 2023). "In line with this potential future application, researchers and clinicians have already evaluated the effect of CXCR4 inhibition on the immune response in various tumor entities." (PMID 36672341, 2023). "The C-X-C motif chemokine receptor 4 (CXCR4) is a key player in tumor growth and the process of metastasis and as such is a highly attractive target in nuclear oncology." (PMID 37597009, 2023). "CXCR4 signaling pathway blockage was found to be beneficial in tumor suppression as CXCR4 contributed to tumor progression, angiogenesis, and metastasis." (PMID 37772226, 2023). "Our studies can be potentially strengthened by analyzing serial tumor biopsies and plasma obtained during tumor progression or response to therapy, such as CXCR4 inhibition, thus providing more dynamic pictures of B cell response and antibody titer changes." (PMID 37751306, 2023). "The level of CXCR4 expression in stromal cells was diminished in non-tumor tissue (8.7 ± 4.6) and higher in tumor pancreatic tissue (23.5 ± 6.1), P-value = 0.022." (PMID 37697316, 2023). "CXCR4 has been described to promote BC cell proliferation and expedite tumor growth via recruiting immune cells and facilitating angiogenesis." (PMID 37784082, 2023). "Recently, it has been suggested that targeting pulmonary tumor microenvironment with CXCR4-inhibiting nanocomplex enhances anti-PD-L1 immunotherapy." (PMID 37350962, 2023). "CXCR4-expressing MM cells promote tumor growth, survival, drug resistance, migration, and homing by transmitting positive signals through interactions with the C-X-C motif chemokine ligand 12 (CXCL12) expressed on BM stromal cells." (PMID 37629558, 2023). "Nataša and group found that the tumor-associated inflammatory mediator prostaglandin E2 (PGE2) regulated CXCL12 production in malignant ascites of ovarian cancer patients, as well as CXCR4 expression on MDSC and its response to CXCL12." (PMID 37497001, 2023). "In a similar way, CXCL12 supports neoangiogenesis while inhibiting endothelial cell apoptosis by binding the receptor CXCR4 present on tumor vessels, or indirectly stimulating leukocyte recruitment." (PMID 36980182, 2023). "Plerixafor derivatives have been found to increase the tumor homing effect of modified nanoparticles by targeting CXCR4 expressed on tumor cells." (PMID 37693046, 2023).
tumor (continued). "Being stimulated by the chemokine CXCL12, the CXCR4 / CXCR7 cascade is involved in tumor proliferation, migration, and metastasis." (PMID 37996954, 2023). "For example, bone marrow stroma secretes C-X-C motif chemokine 12 (CXCL12), which attracts NSCLC tumor cells expressing its receptor C-X-C chemokine receptor 4 (CXCR4), directing tumor cells from blood circulation to the bone." (PMID 38002256, 2023). "It has been reported that zerumbone is a novel inhibitor of chemokine receptor-4 (CXCR4) expression, which mediates homing of tumor cells to specific organs during metastasis, suggesting the potential of the product in the suppression of cell metastasis." (PMID 35931788, 2023). "Intraindividual comparison of CXCR4 expression between primary tumor and metastasis would further increase data value; a potential approach would be the design and evaluation of larger prospective tissue biobanks." (PMID 36982302, 2023). "Examples are bone specific alkaline phosphatase in serum, urine N-terminal telopeptide in urine and C-X-C- Motif Chemokine Receptor 4 on the tumor." (PMID 37213294, 2023). "CXCR4 activation triggers intracellular signaling pathways in the TME that are correlated with aggressive tumor behavior." (PMID 38004606, 2023). "Polarization of M2 phenotype to M1 phenotype is promoted when CXCL12 and CXCR4 expression is downregulated in tumor cells." (PMID 36173487, 2023). "Stromal cell derived factor 1 (SDF-1)/chemokine receptor 4 (CXCR4) is an important signaling axis that mediates the communication between tumor and stromal cells." (PMID 37670388, 2023). "CXCR4 and CXCR7, both CXCL12 receptors, are highly expressed in PTC and are associated with tumor progression." (PMID 38250858, 2023). "Overall, more than 3/4 (77.1%) of the analysed tumours showed CXCR4 protein expression, with nearly half (48.6%) of all samples showing a strong IHC staining with a score of 2 or above and one-fourth (25.7%) of them at high expression levels (Score 3)." (PMID 37047331, 2023). "The latest research has shown a shift towards antagonists and α-emitters, as well as a pan-cancer approach that targets more widely expressed components of the tumor microenvironment, such as CXCR4 and FAPI radioconjugates." (PMID 37376181, 2023). "We also identified the direct mechanism that CXCR4 upregulation is a response of the tumor cells to docetaxel, and AMD3100 blocks the protective adaptation." (PMID 37280713, 2023). "CXCR4 protein plays a critical role in homing MSCs for tumor cell metastasis through the SDF-1/CXCR4 axis." (PMID 37717008, 2023). "CXCR4 is frequently overexpressed in invasive breast cancer and has an important role in tumor migration, invasiveness, metastasis, and proliferation." (PMID 36832085, 2023). "In a micro-PET/CT imaging study and biodistribution study, [64Cu]NOTA-CP01 was injected into EC109 tumor-bearing mice (CXCR4-positive)." (PMID 37375261, 2023). "When SDF-1 engages with its receptor, CXCR4, predominantly present on pancreatic cancer cells, it modulates tumor cell proliferation, malignancy, and resistance to chemotherapy." (PMID 37958483, 2023). "Our data also suggest that miR-1 mediated CXCR4 modulations require FOXM1 pathway activity to promote tumor growth and metastasis." (PMID 36597126, 2023). "Stromal derived factor 1 (SDF-1) secreted by CAF binds to CXCR4 on the surface of tumor cells and vascular endothelial cells (ECs), increasing tumor growth and malignancy as well as promoting angiogenesis." (PMID 37178254, 2023). "Another mechanism of AMD3100 antitumor activity was to block CXCR4+ tumor cells from interacting with CXCL12 produced by cancer associated fibroblasts." (PMID 37114134, 2023). "CXCL12, which is involved in CXCR4-mediated recruitment of CD8+ T cell recruitment to the tumor microenvironment, was upregulated by ionizing radiation in MOC2 cells but not in LY2, SCC83, and CAL27 HNSCC cells." (PMID 37444444, 2023).
tumor (continued). "Our results revealed a high CXCR4 expression in the tumor stroma, which is related to a poor tumor differentiation." (PMID 37697316, 2023). "Due to the association between PGCCs and tumor-initiating cells/CSCs, we applied 4 ALDH inhibitors, 2 WNT inhibitors, and 2 CXCR4 inhibitors." (PMID 38129519, 2023). "Peptide R impaired the metabolic activity and cell proliferation of the U87 cell line, reducing CXCR4 expression and cell migration in vitro while decreasing tumor cellularity and modulating M1 features in the orthotopic in vivo model." (PMID 36980182, 2023). "Together, our analyses of vessel structure and markers of hypoxia show that CXCR4 inhibition differentially promoted the normalization of tumor vasculature in bony metastatic versus primary PtenSmad4-null murine PCa lesions." (PMID 36831366, 2023). "Signaling by the chemokine receptor CXCR4 after binding the chemokine CXCL12 (SCF-1) triggers increased tumor proliferation, survival, and chemotaxis." (PMID 37114134, 2023). "The number of mast cells in TEM also correlates with tumor grade, and their degranulation within the tumor leads to the release of chemokines and other tumor-promoting compounds such as CXCR4, STAT3 and serglycin which trigger further tumor progression." (PMID 38275375, 2023). "Recent proof-of-concept studies were performed for breast, cervical, and ovarian cancer showing anti-tumor effects of CXCR4 antagonists (in combination with conventional therapy) in vivo." (PMID 36725964, 2023). "Among all tested tumor entities (in total, n = 35), hematologic malignancies revealed the highest in vivo CXCR4 expression (determined by SUVmax) and elevated target-to-background ratios." (PMID 37290799, 2023). "Given the known role of CXCR4 signaling in the tumor/immune microenvironment, to better understand how CXCR4 signaling contributes to trastuzumab resistance, it should be noted that we used 3D co-cultures or 3D Matrigel culture with the supplement of SDF-1α." (PMID 37280713, 2023). "IFNg-induced downregulation of CXCR4 was previously shown to result in reduced tumor metastasis and virus replication." (PMID 38086798, 2023). "CXCL12 in the tumor microenvironment is mostly produced by CAF and plays a crucial function in attracting myeloid cells and supporting an immunosuppressive phenotype; inhibition of CXCL12 or its receptor CXCR4 lowers the amount of MDSC in the tumor." (PMID 37007004, 2023). "Using multiple trastuzumab-resistant cell lines and an in vivo established trastuzumab-resistant xenograft mouse model, we demonstrated that targeting CXCR4 with AMD3100 suppresses tumor growth in vitro and in vivo, and synergizes with docetaxel." (PMID 36824840, 2023). "The co-injection of AMD3100 (5 mg/kg i.v.)showed a reduction in the uptake in all these organs (up to 94% in liver), including the xenografted u87.CXCR4 tumor." (PMID 37318633, 2023). "Next, CD44 + MKN45 cells transfected with sh-NC or sh-CXCR4 were injected subcutaneously or into the tail vein of nude mice to observe tumor growth and liver metastasis." (PMID 37679408, 2023). "One chemokine was examined, CXCR4 siRNA liposome complexes, and this therapy showed a 39.2% reduction (0.398 ± 0.062 g; p < 0.01) in tumor weight compared to the 8.9% reduction (0.655 ± 0.034 g; p > 0.01) in the empty liposome control group." (PMID 37612696, 2023). "The SDF-1 and CXCR4 signaling pathway was considered to have roles in angiogenesis, tumor growth, embryogenesis, and wound healing." (PMID 38075689, 2023). "The SDF-1/CXCR4 axis has been well investigated and displays a major role in inducing the tumor homing of MSCs." (PMID 38049868, 2023). "A high expression of CXCR4 in the cytoplasm or membrane of tumor cells is often a predictor of a poor prognosis." (PMID 37444550, 2023). "Some of the upregulated immune checkpoints, including CXCR4, are expected to become new immunotherapeutic targets, which can achieve anti-tumor effects together with PD-1/PD-L1 inhibitors." (PMID 37025405, 2023).
tumor (continued). "In PET studies, [18F]MCFB showed almost two-fold higher uptake in the U2932 tumor than in the SuDHL8 tumor, which is consistent with the CXCR4 expression level." (PMID 37375261, 2023). "Studies have shown that STEAP4 can promote PCa cell proliferation, and CXCR4 participates in the activation of various pro-cancer regulatory mechanisms, thereby promoting tumor proliferation and metastasis." (PMID 37221625, 2023). "The possible reason for this is that knockdown of CXCR4 triggers different downstream signals in tumor cells, leading to a decrease in inflammatory factors." (PMID 37626511, 2023). "BM-MSCs were engineered by overexpression of CXCR4 to actively migrate toward the tumor sites by identification of fluorescent NPs." (PMID 38004925, 2023). "Once we proved the fundamental role of the stroma in tumor samples, we decided to analyze the CXCR4 expression in different cell components of our samples." (PMID 37697316, 2023). "The tumor endothelium in HCC is characterized by a high expression of CXCR4, a marker for neoangiogenesis." (PMID 36845555, 2023). "By blocking CXCR4 with AMD3100 in murine models, CD8+ TIL and macrophage infiltration are promoted, causing tumor cell death." (PMID 37784082, 2023). "In PCa bone metastasis, ac-KLF5 (acetylated KLF5) up-regulates CXCR4 expression through histone acetylation in the promoter region of CXCR4 gene, and further promotes IL-11 secretion, osteoclast differentiation and the regulation of tumor cell plasticity." (PMID 37190171, 2023). "In clear cell renal cell carcinoma, the forced downregulation of neuritin expression in patient-derived spheroid cultures decreased CXCR4 levels and suppressed tumor cell growth." (PMID 37092449, 2023). "Using a panel of trastuzumab-resistant cell lines and an in vivo established trastuzumab-resistant xenograft mouse model, we demonstrated that targeting CXCR4 with AMD3100 suppresses tumor growth in vitro and in vivo, and synergizes with docetaxel." (PMID 37280713, 2023). "Pharmacological inhibition of CXCR4 using AMD3100 to prevent PvTAM accumulation reduced tumor recurrence in a murine Lewis Lung carcinoma model post cyclophosphamide treatment, providing a therapeutic strategy to block these effects." (PMID 37199172, 2023). "For instance, stromal cell-derived factor-1 (SDF-1), acting as an important ligand of CXCR4 and chemoattractant for MSCs, is constantly secreted by tumor cells." (PMID 38049868, 2023). "We also detected a differential distribution for the expression of these markers: CXCR4 was primarily and uniformly expressed in PCa cells, while SDF1α expression was seen predominantly in the tumor stroma." (PMID 36831366, 2023). "In fact, CXCR4 is a promising therapeutic target against cancer since the intracellular siRNA delivery of its knockdown can prevent tumor growth." (PMID 38004925, 2023). "In in vivo studies carried out in nude mice bearing human small cell lung cancer tumor xenografts, 68Ga3+-labeled CPCR4-2 showed CXCR4-specific tumor uptake, fast renal excretion, and high tumor-to-muscle ratios." (PMID 37375261, 2023). "We found that, in LUAD, CXCR4 was moderately negatively correlated with tumor purity, and moderately positively correlated with the tumor infiltration of B cells, CD8+ T cells, CD4+ T cells, macrophages, neutrophils, and DC cells." (PMID 36308553, 2023). "As examples, MIF-(CD74 + CXCR4) interaction was decreased between tumor and most immune cell types post-treatment." (PMID 36417130, 2023). "In a pro-tumor model induced by Pit-1, Pit-1 exerted a pro-angiogenic effect through increasing the expression of CXCR4 and CXCL12." (PMID 37497001, 2023). "CXCR4 and CXCR7 expression is associated with large tumor size, advanced TNM staging, and short overall and recurrence-free survival in FTC." (PMID 38250858, 2023).